HCN1 (hyperpolarization activated cyclic nucleotide gated potassium channel 1)
Diseases named in the same sentence as HCN1 in open-access papers (continued):
Sharing a sentence is not in itself a finding about the gene and the disease.
anxiety disorder (1 paper, 2022). A category of psychiatric disorders which are characterized by anxious feelings or fear often accompanied by physical symptoms associated with anxiety. "Antianxiety behavior associated with the brain-derived neurotrophic factor-mammalian target of rapamycin signaling pathway was revealed by knockdown of HCN1 channels in the hippocampal dorsal CA1 region, suggesting that HCN1 protein might be a target for anxiety disorder treatment." (PMID 35372451, 2022).
Bradycardia (1 paper, 2023). A slower than normal heart rate (in adults, slower than 60 beats per minute). "In addition, HCN1 plays an important role in the regulation of cardiac pacemaker activity and rhythmic neuronal activity, and inhibition of HCN1 may induce bradycardia and cardiac arrest." (PMID 37781698, 2023).
cardiac hypertrophy (1 paper, 2021). "In the present study, the selective upregulation of Hcn1 gene is consistent with previous studies using a mouse model of cardiac hypertrophy, although Hcn2 and Hcn4 are more abundant than Hcn150." (PMID 34489488, 2021).
diabetes (1 paper, 2018). "At the same time, several conditions such as nerve injury, antineoplastic agents and diabetes appear to increase HCN1 expression and function." (PMID 30467478, 2018).
Dystonia (1 paper, 2025). An abnormally increased muscular tone that causes fixed abnormal postures. "HCN2 variants phenotypic spectrum also include dystonia and movement disorders, which have not been yet reported in individuals with HCN2 or HCN1 variants." (PMID 40468825, 2025).
glioma (1 paper, 2017). A benign or malignant brain and spinal cord tumor that arises from glial cells (astrocytes, oligodendrocytes, ependymal cells). "FSTL5, HCN1, TMEM132D, TRHDE and KRT222 showed the strongest expression correlation with other genes in the co-expression network of glioma tissues." (PMID 29046615, 2017).
injury (1 paper, 2020). Damage inflicted on the body as the direct or indirect result of an external force, with or without disruption of structural continuity. "For example, a downregulation in HCN1 subunit expression (which confer faster kinetics on HCN channel complexes) in iPVINs, coupled with an increased expression of the more slowly conducting HCN4 subunits, could contribute to the reduced excitability seen in these cells after nerve injury." (PMID 33029722, 2020).
MELAS (1 paper, 2021).
motor neuron disease (1 paper, 2018). "A major question arising from our results is whether this novel function of VAPB in regulating HCN1 and HCN2 activities could be involved in motor neuron disease." (PMID 29879376, 2018).
Parkinson disease (1 paper, 2016). A progressive degenerative disorder of the central nervous system characterized by loss of dopamine producing neurons in the substantia nigra and the presence of Lewy bodies in the substantia nigra and locus coeruleus. "Aberrant SUMOylation has been linked to neurological diseases that also display alterations in HCN1 and HCN2 channel expression, such as seizures and Parkinson’s disease." (PMID 28127275, 2016).
stress-related disorder (1 paper, 2025). Stress-related disorders are mental health disorders that are a result of an atypical response to both short and long-term anxiety due to physical, mental, or emotional stress. "Together, these findings underscore the behavioral relevance of HCN1 dysregulation in the hippocampus and position it as a promising target for alleviating cognitive and emotional symptoms in stress-related disorders." (PMID 40671804, 2025).
tauopathy (1 paper, 2024). Neurodegenerative disorders involving deposition of abnormal tau protein isoforms (tau proteins) in neurons and glial cells in the brain. "Progressive increases in HCN1 and HCN3 ion channel expression are accompanied by an array of dendritic, synaptic, and ultrastructural changes as well as the development of tau pathology in Tau35 mice, with decreases in dendritic branching observed only during advanced tauopathy." (PMID 38994745, 2024).
cancer (9 papers, 2009 to 2023). A tumor composed of atypical neoplastic, often pleomorphic cells that invade other tissues. "It is significant that none of the stage-salient genes figure as a cancer gene or a hallmark gene in the Cancer Gene Census; HCN1 is notably marked as a candidate cancer gene based on mouse insertional mutagenesis experiments." (PMID 35202405, 2022). "Seven genes were expressed in non-cancerous tissues only, including LINC01612 (TSG), FAM3D (inflammation), HCN1, and CNBD1 (mutation in cancer) and three other genes." (PMID 37509325, 2023).
tumor (6 papers, 2018 to 2024). "Notably, several mutations (5× BRCA2, 4× ERBB2, 2× NRAS, 2× HCN1 [hyperpolarization-activated cyclic nucleotide-gated potassium channel 1]) were detected more than once in plasma or stool samples across all patients but never in tumor biopsies." (PMID 38766867, 2024). "Sixteen nearby genes showed higher expression in non-cancerous tissues, including seven with almost no expression in tumor (HCN1, SLC22A2, FAM3D, LRFN5, LINC01612, LINC02512, and CNBD1)." (PMID 37509325, 2023).
neurological disorders (4 papers, 2016 to 2024). "Dysfunction in HCN1 channels can lead to neuronal hyperexcitability and hypersynchronous firing, phenomena associated with various neurological disorders." (PMID 39307309, 2024). "Changes in the expression of voltage‐gated channels encoded by the HCN1–4 gene family have been reported in multiple neurological disorders." (PMID 38994745, 2024). "Considering that HCN1 is the primary isoform expressed in the central and peripheral nervous systems, it stands out as a promising target for addressing neurological disorders." (PMID 39307309, 2024). "Despite growing evidence supporting the therapeutic potential of HCN1 inhibition in treating neurological disorders, the structural basis of channel inhibition by inhibitor has remained elusive." (PMID 39307309, 2024). "Of note, previous evidence showed that the expression of HCN1 and SCN10A exhibit sex differences in several nerve tissues, which might contribute the different prevalence of neurological disorders." (PMID 38289829, 2024).
psychiatric disorder (2 papers, 2020). A disorder characterized by behavioral and/or psychological abnormalities, often accompanied by physical symptoms. "In regard to Ih, two medications, lamotrigine and gabapentin, used for various neurological and psychiatric disorders, upregulate HCN1 levels." (PMID 32958782, 2020). "Previously, the Hcn1 gene has not been associated with alcohol use, but there has been some evidence indicating it has a role in psychiatric disorders." (PMID 33105624, 2020).
cardiac diseases (1 paper, 2020). "Previous studies have shown that many cardiac diseases can cause remodeling of major ion channels including HCN1 and HCN4, A1R, and L-type calcium channels." (PMID 31980605, 2020).
movement disorder (1 paper, 2025). Neurological conditions resulting in abnormal voluntary or involuntary movement, which may impact the speed, fluency, quality and ease of movement. "Another difference between HCN1 and HCN2 variants is the lack of movement disorders reported so far for individuals with the HCN1 variants." (PMID 40468825, 2025).
HCN1 also shares sentences with these, for which no sentence is quoted: Intellectual disability (4 papers); channelopathies (2); early infantile epileptic encephalopathy (2); febrile seizures (2); infantile epileptic encephalopathy (2); neurodevelopmental disorder (2); Seizure (2); alcohol use disorders (1); Bartter syndrome type 4 (1); brain disorder (1); brain ischemia (1); breast tumour (1); cannabis abuse (1); cardiac arrest (1); cardiac arrhythmia (1); cortical dysplasia (1); encephalopathies (1); Epileptic spasm (1); focal epilepsy (1); fragile X syndrome (1); hearing loss (1); heroin dependence (1); infection (1); ischemia (1); melanoma (1); microcephaly (1); myocardial infarction (1); myoclonic-atonic epilepsy (1); myoclonic-atonic seizures (1); neuromuscular disease (1).
A further 3 diseases each share a sentence with HCN1 in 1 paper.